CD4 (CD4 molecule)
Diseases named in the same sentence as CD4 in open-access papers (continued):
Sharing a sentence is not in itself a finding about the gene and the disease.
tumor (continued). "Recent reports have provided evidence that CD4+ Th cells can recognize tumor-specific neoantigens in human solid tumors, and their presence is associated with tumor regression in murine models and in humans." (PMID 35439168, 2022). "Increasing studies have assessed the contribution of cytotoxic cells, especially CD8 T cells; however, recent studies have revealed that CD4 T cells exert their antitumor effects by directly inhibiting the tumor cell cycle." (PMID 36532062, 2022). "Combining anti-OX40 and anti-CTLA-4 immunotherapy boosted tumor regression and tumor-bearing host survival depending on CD4+ and CD8+ T cells." (PMID 35585567, 2022). "Here, We used T-cell receptor transgenic mice specific for CD4+ T cell epitopes LCMV-GP 66-77 (SMARTA mice) and OVA 323–339 (OT-II mice) as models to study tumor-specific CD4+ T cells during cancer immunotherapy." (PMID 35784297, 2022). "OAS1 was overexpressed in C13 CD4 T cell clusters /C4-GZMK/C4-CD69 CD8/CD4 T cell clusters and suppressive tumor Tregs of CD4-C9CTLA cells vs. other tumor-infiltrating Tregs of CD4-C8-FOXP3 cells." (PMID 35804895, 2022). "A strong negative correlation was observed between frequencies of FoxP3−Helios− T cells and CD4+PD-1+ T cells in TILs in both early and advanced tumor stages, and in NILs with early tumor stages." (PMID 36146549, 2022). "The circCsnk1g3-silenced tumors showed a significantly decreased ratio between tumor cells and T cells, both CD4+ and CD8+, compared to the controls." (PMID 36433954, 2022). "Peripheral blood tumor-specific CD4+ T cells obtained from ex vivo sorted cells from patient samples effectively lysed MHC-II-expressing target cells." (PMID 36159781, 2022). "On the other hand, CD4+ helper T cells present in the TME are involved in activating CTLs against tumor cells." (PMID 36072957, 2022). "CD4+ Th-2 cells secrete cytokines that have been reported to play a role in tumor growth and metastasis, such as IL-4, IL-5, and IL-13." (PMID 36551522, 2022). "We show here that women with CRC have increased CD4+ T cells in tumor tissue, uninvolved peri-tumoral tissue, and metastatic lymph nodes as compared to men." (PMID 36387163, 2022). "Tumor tissues with enriched infiltration of immune cells, such as CD4 and CD8 T cells, are defined as “immune-inflamed” or “hot” tumors." (PMID 35150340, 2022). "Tumor-infiltrating lymphocytes (TILs) present in TME include CD4 + helper cells, immunosuppressive CD4 + FOXP3 + regulatory T-cells (Tregs) and CD8 + cytotoxic T-cells (CTLs)." (PMID 36253762, 2022). "Regulatory T cells (Tregs) are a subset of CD4+ T cells, which have been known for their immunosuppressive roles in various conditions including anti-tumor immune responses." (PMID 35812393, 2022). "For instance, the inhibitory checkpoint molecule PD-1 is expressed not only on the tumor-targeting immune cells (such as on cytotoxic CD8+ T cells) but also on the tumor-protecting immune cells as regulatory CD4+ T cells." (PMID 36232398, 2022). "To determine if the effectiveness of tumor only irradiation combined with anti-CD25 was dependent on CD4 and/or CD8 T cells, we pharmacologically depleted either CD4 T cells, CD8 T cells, or both cell types." (PMID 36385142, 2022). "Further, TEX induced immune suppression by proapoptosis of antitumor CD8+ effector T cells and enhancing suppressor activity of CD4+ T regulatory cells, thus contributing to tumor escape." (PMID 35163380, 2022). "In mice, successful treatment of bladder tumors with intravesical BCG results in long term tumor-specific immunity that is primarily dependent on CD4 T cells." (PMID 35804844, 2022). "The PRGN-2009 monotherapy in the syngeneic TC-1 model also reduced tumor volumes and weights, generated high levels of HPV16 E6–specific T cells, and increased multifunctional CD8+ and CD4+ T cells in the tumor microenvironment." (PMID 35756634, 2022).
tumor (continued). "Infiltration of CD3, CD8, and CD4 lymphocytes in the tumor and adjacent normal lung tissues was assessed by immunohistochemical staining." (PMID 35187162, 2022). "Their high frequency among CD4+ T cells in tumor-infiltrating lymphocytes or a high ratio of FOXP3+ Treg cells to CD8+ T cells is associated with worse prognosis, especially in patients with breast, gastric, and ovarian cancer." (PMID 35759090, 2022). "There appears to be an increase in Tim-3 expression on tumour-infiltrating CD4+ T cells and a significant increase on CD8+ T cells compared with circulating levels in the treatment-naïve setting (p = 0.06 and p = 0.009)." (PMID 35366537, 2022). "Cytotoxic CD8 T cells and CD4 helper T cells specifically target antigenic tumor cells to inhibit tumor growth." (PMID 35368886, 2022). "Recently it has been shown that the mechanism of CD4 CTL-mediated killing of tumor cells is largely similar to that of CD8+ effector cells, but with delayed kinetics." (PMID 35903098, 2022). "The pulsed radiation expanded tumor-specific CD4+ T cells and increased central as well as effector memory." (PMID 36275767, 2022). "In line with results from Asm-KO mice, we detected elevated percentages of tumor-infiltrating Foxp3+ Tregs as well as reduced frequencies of CD4+ and CD8+ T cells in dLNs from Asm/CD4cre mice compared to control littermates." (PMID 36426850, 2022). "For example, tumor-infiltrating CD4+ and CD8+ T lymphocytes play an antitumor role, which is associated with favorable prognosis." (PMID 35355983, 2022). "We found that tumor-infiltrating CD4 + T cells were comparable between KrasG12D-sgControl tumors and KrasG12D-sgZNF24 tumors." (PMID 36457047, 2022). "During cancer progression, CD4+ T cells are required for efficacious antitumor immunity since they can target tumor cells, either directly through cytolytic mechanisms or indirectly by modulating the tumor microenvironment (TME)." (PMID 36428596, 2022). "Within TIL from RencaHA tumor-bearing mice 86 ± 2% of CD25+FoxP3+CD4+ T cells expressed both CD39 and CD73." (PMID 35013519, 2022). "In multiple mouse models, depletion of CD4+Th1 cells reduced pericyte coverage and increased aberrant tumor vessels, while activation of CD4+Th1 cells improved vascular normalization." (PMID 36569915, 2022). "Cytotoxicity-related genes GNLY, NKG7, GZMB and GZMA were downregulated in both tumor-derived CD4+ and CD8+ T cells." (PMID 36506053, 2022). "There are also few reports on the ability of CD4+ T cells to function as effector cells in mice rejecting tumor rechallenge." (PMID 36159781, 2022). "Combinatorial treatment induced protective immune response, increased CD4+ T-cells in tumor and decreased tumor necrosis factor-alpha in serum." (PMID 36144329, 2022). "Another study identified a new subset of CD4+ Th-CXCL13 with tumor-resident gene characteristics in NPC." (PMID 35663939, 2022). "Collectively, RUNX3 can strongly influence anti-tumor immunity of CD4+ CTLs via direct or indirect pathways." (PMID 36231078, 2022). "CD4+ T cells have the dual function both in killing tumor cells directly and in maintaining and promoting CD8+ T cells survival." (PMID 35692574, 2022). "Cryo-thermal CD4+ T cells also induced high expression of IL-12 in DCs and maintained a high level of IL-12 in macrophages compared to tumor-bearing CD4+ T cells." (PMID 35874660, 2022). "Once peripheral blood monocytes are recruited to the tumor, they rapidly differentiate into the M2 macrophages via induction of IL-4 and IL-10 derived from tumor cells, Th2-polarized CD4+ cells and regulatory T cells." (PMID 35210436, 2022). "Tissues from patients with low numbers of CD4+ T cells within 20 μm of the tumor secreted less MIF and there was a negative correlation between MIF levels and numbers of CD4+ T cells within and 20 μm of the tumor nests." (PMID 35954489, 2022).
tumor (continued). "Citrullinated GRP78 189-208 peptide was detected with linearity value (R2) of greater than 0.90 and compared to detection of two vimentin and one alpha-enolase peptides known to be CD4 T cell targets in the same tumour model." (PMID 36544781, 2022). "EBV-CTL are CD3+ T-cells (both CD4+ and CD8+ subtypes at different ratios according to donor and selection technique) capable of recognizing EBV-associated antigens on tumor cells." (PMID 36556158, 2022). "These two experiments show that both vaccine-elicited endogenous CD4 T cells as well as transferred TCR transgenic CD4 T cells are necessary for tumor rejection in immune-competent mice." (PMID 35903540, 2022). "The proportion of CD3 + cells to total immune cells and CD4 + T-cells to total immune cells tended to be inversely correlated with HK2 tumor expression (spearman rho = −0.283, P = 0.077; spearman rho = −0.326, P = 0.040, respectively)." (PMID 36320008, 2022). "The number of MDSCs and T-regs (Foxp3+CD25+CD4+ cells) isolated from the spleen of Sunitinib-treated tumor-bearing mice was reduced in a dose-dependent manner." (PMID 36555334, 2022). "Macrophages secrete CCL22 to induce Treg migration to the tumor area and inhibit the activation of CD4 (+) CD25 (-) T cells, resulting in poor prognosis in the high-risk group." (PMID 36324575, 2022). "The C2 tumour type consisted of important activated immune cells such as NK cells, CD4 memory T cells, mast cells, and dendritic cells, while in the C1 tumour type, B cells, dendritic cells, and memory T cells were at a resting state." (PMID 36010915, 2022). "We then assessed by flow cytometry activation markers associated with effector function (CD69, CD44 and 2-NDGB) expressed on tumor infiltrating CD4+ and CD8+ T cells from anti-PD-1 and anti-PD-L1 refractory mice." (PMID 35355980, 2022). "In the TME, high levels of IL-4 produced by CD4 T cells, tumor cells, and other cell types drive the immunosuppressive phenotype of TAMs through the STAT6 pathway." (PMID 35179953, 2022). "Immune system-wise, bleomycin ECT increases the infiltration of CD8+ T lymphocytes into the tumours by recruiting dendritic cells (DCs), while the presence of CD4+ T cells remains stable." (PMID 36551739, 2022). "We observed that Mito‐ATO significantly increased tumor infiltrating CD4+ T cells, and also resulted in a significant reduction of G‐MDSCs and Foxp3+ Tregs within tumors receiving Mito‐ATO treatment." (PMID 35243806, 2022). "Consistent with published data, anti-PD-L1 alone significantly reduced the mortality and repressed tumor growth, with results comparable to those in the CD4+ T-cell adoptive transfer group." (PMID 35784297, 2022). "In particular, CD4(+) Tregs expressing the transcription factor forkhead box P3 (FOXP3) are abundant in tumor tissues, where they appear to hinder the induction of effective antitumor immunity." (PMID 35358193, 2022). "The responses include enhanced tumor infiltration by CD4+ helper T cells, CD8+ cytotoxic T cells, and mature dendritic cells; the significantly decreased level of immune suppressed regulator T cells." (PMID 35907841, 2022). "In many tumor environments regulatory cells and CD4+ T-cells would dominate the response and produce an immune tolerant microenvironment." (PMID 36457578, 2022). "CTLA-4 was significantly increased on the surface of tumour-infiltrating CD4+ T cells compared with those in circulation in the treatment-naïve setting (p = 0.03)." (PMID 35366537, 2022). "Pre- immunotherapy butyrate supplement improved anti-PD-1 efficacy in mice humanized with gut microbiota from CRC patientsButyrate increased infiltration of tumor-killing CD4+ and CD8+ cells in the tumor." (PMID 36296324, 2022). "IHC/ImmunoPath and mass cytometry revealed similar trends for tumor cell percentage and CD4/CD8 ratio." (PMID 34165864, 2022). "RFA treatment improves the tumor immune microenvironment by increasing the infiltration of CD4+ and CD8+T cells and reducing Tregs proportion." (PMID 36131929, 2022).
tumor (continued). "FL tumor cells modulate gene expression of CD8+ and CD4+ cells, and the survival of FL tumor cells is dependent on surrounding CD4+ T cells." (PMID 35268349, 2022). "After MC38 tumor challenge, Rag1-KO mice reconstituted with PTEN-deficient CD8+ T cells plus WT CD4+ T cells had enhanced antitumor immunity." (PMID 35143421, 2022). "We also find a prominent in situ activation of CD4+ T cells in WT and B2m-/- B16 tumor-bearing lungs." (PMID 36733396, 2022). "Our studies reveal that cell surface PD-1H is upregulated in TILs in mouse tumor models and both CD4+ and CD8+ TILs maintain PD-1H expression." (PMID 34905507, 2022). "It is important to elucidate the functions of CD4-derived TGF-β in tumor vaccine settings in the future." (PMID 36229613, 2022). "The expression of MHC class I is necessary for tumor recognition and destruction by T cells, and the ability of CD4+ and CD8+ T cells to infiltrate tumors can have a direct correlation with the level of MHC class I expression." (PMID 36297510, 2022). "Tumor infiltration is associated with six cell types: B cells, CD8+ cells, CD4+ cells, macrophages, neutrophils, and dendritic cells." (PMID 36193307, 2022). "Meanwhile, CD4+ Th1 can activate antigen-presenting cells (APCs) and maintain the effect of tumor-specific CD8+ T cells." (PMID 35203498, 2022). "Autophagy-deficient monocytic MDSCs (M-MDSCs) results in efficient activation of tumor-specific CD4+ T cells and improved anti-tumor immunity." (PMID 36003368, 2022). "It has been also demonstrated that in tumor microenvironment, tumor cells can recruit CD4+ T cells to disturb the cytotoxic functions of CD8+ T cells." (PMID 36482354, 2022). "Correlations between frequencies of FoxP3+ Tregs and CD4+TIM-3+ T cells in TME were stronger in advanced tumor stages, compared to early stages (r = 0.737, p = 0.023 [early]; r = 0.818, p = 0.0006 [advanced])." (PMID 36146549, 2022). "The distribution difference of TIICs between tumor and normal groups was calculated by the Wilcoxon rank-sum test, which depicted that naive B cells, plasma cells, resting memory CD4 T cells, and resting dendritic cells were significantly lower in ccRCC." (PMID 35320950, 2022). "We also found greatly increased levels of CD4+CD8+ T -cells in the tumor (+ 1.7%, p < 0.005), lungs (+ 0.07%, p < 0.05), and blood (+ 2%, p < 0.005) of DC-iMB treated animals compared to marginal levels of both T-cell types in the other groups." (PMID 36224614, 2022). "These tumours show low infiltration by CD8+ T lymphocytes, CD4+Th1 T helper cells and NK cells, all of which are to a greater or lesser extent effectors of the anti-tumour response." (PMID 35954497, 2022). "The depletion of TGF-β-R2 in CD4+ T cells impedes tumor progression as a result of tissue healing and remodeling of the blood vasculature, resulting in tumor cell hypoxia and death in distant avascular regions." (PMID 36233088, 2022). "For HL, combined blocking of LAG-3 and PD-1 has stronger anti-tumor immunity mediated by CD4+T cells than single treatment." (PMID 36561512, 2022). "In recurrent nasopharyngeal carcinoma, circ0000831, circ0006935, circ005019, circ0031584 and circ0001730 have been shown to induce tumor microenvironment changes, affecting distribution of immune cells, as well as a decrease in the ratio of CD4+/CD8+ T cells." (PMID 35186039, 2022). "CD103+ CD4+ T cells exhibit an immunosuppressive phenotype and high retention capacity in GC tumor tissues, leading to CD8 + T cell dysfunction, and granzyme B (GZMB), interferon-γ (IFN-γ), tumor necrosis factor α (TNF-α), and perforin (PRF-1) reduction." (PMID 36341377, 2022). "Based on these lines of evidence, we and others have investigated the exhaustion of CD4 T cells at the tumor site." (PMID 35954341, 2022).
tumor (continued). "proved that radiotherapy combined with anti-CD25 monoclonal antibody therapy reversed the increase of PD-1 expression on CD8+ T cells and CD4+ T cells during the radiotherapy, thereby inhibiting the tumor growth and improving the overall survival rate." (PMID 35371055, 2022). "Tumor-infiltrating lymphocytes (TILs) contain substantial numbers of CD4+ T cells mediating pro- and antitumor functions." (PMID 35703176, 2022). "The molecular risk score based on co-expression of Gal-9, CD4, CD3, PD-1 and PD-L1 on tumor cells was an accurate predictor of OS in both the entire cohort and the test cohort." (PMID 36263183, 2022). "Specifically, the intrinsic tumor immunity and the associated anti-PD-1 MOA were predominately driven by CD8+ cytotoxic TILs (CTL) in all syngeneic tumors, excluding Hepa1-6 where CD4+ Teff TILs played a key role." (PMID 35228603, 2022). "Projection of these data into the reference map showed that most tumor-specific CD4+ T cells in the dLN corresponded to Tfh states, similarly to virus-specific cells in the LN of infected animals." (PMID 35829695, 2022). "These LOFU treatments overcame T cell hypo-responsiveness to tumour antigens by increasing the production of cytokines by the re-stimulated CD4+ T cells, and by reducing anergy-related gene expression." (PMID 35158903, 2022). "Despite these indirect functions, CD4+ T cells can eliminate tumor cells directly through the release of granzyme B and perforin and through the induction of apoptosis via FAS-FAS ligand." (PMID 35326515, 2022). "Paired tumor tissues were stained immunohistochemically to study the number and location of CD4+ and CD8+ T cells in central and peripheral tumor tissues and quantified using QuPath." (PMID 35954489, 2022). "This study identified four hub genes whose expression correlated to CD4+ T cell infiltration level, which prompted a possible mechanism to promote tumorigenesis and tumor progression." (PMID 35711924, 2022). "A more in-depth analysis using immunofluorescence staining revealed that treating tumor-bearing mice with attenuated Salmonella decreased the ratio of Tregs/CD4+ T cells within the tumor tissue." (PMID 36605208, 2022). "In this study, we first demonstrated a statistical positive correlation between the mRNA expression of LMNB1 and the infiltration level of CD4+ Th2 cells in all the TCGA tumor types excluding UCS." (PMID 35241075, 2022). "In the current study, RT was observed to significantly up-regulate the proportion of Tregs in CD4+ T cells in tumor tissues, and significantly down-regulate the number of CD45+ leukocytes in tumor tissues and the spleen." (PMID 36429033, 2022). "Autophagy-deficient MDSCs displayed reduced lysosomal degradation, which promoted the surface expression of MHC class II molecules and resulted in the effective activation of tumor-specific CD4+ T cells." (PMID 36300110, 2022). "CD4+ memory T cells were present in the primary tumor, ascites, and metastases, whereas CD8+ memory T cells were only present in primary tumors and metastases." (PMID 36077756, 2022). "Herein, CD4+ T cells, especially Th1/Th17 cell subsets, were found to inhibit the expression of inhibitory receptors on CIKs, enhance the tumor-killing function of CIKs, and promote the migration and locomotion of CIKs." (PMID 35523765, 2022). "In tumors derived from the murine KLN205 cancer cells, sitravatinib significantly reduced the proportion of PD-L1-expressing-MDSCs and tumor-associated macrophages among CD11b+ cells and increased T-cell infiltration (CD3+, CD4+ CD8+, Ki67+ PD-1+ CTLA-4+)." (PMID 35572601, 2022). "These unique tumor-infiltrating CD4+ T cells express the transcription factor BHLHE40, the effector cytokine IFN-γ, and the CXC chemokine receptor (CXCR) 5, all of which are known to be expressed in TH1 cells." (PMID 35759090, 2022).